CRP (C-reactive protein)
Diseases named in the same sentence as CRP in open-access papers (continued):
Sharing a sentence is not in itself a finding about the gene and the disease.
familial Mediterranean fever (10 papers, 2010 to 2025). Familial Mediterranean fever (FMF) is an autoinflammatory disorder characterized by recurrent short episodes of fever and serositis resulting in pain in the abdomen, chest, joints and muscles. "In a study that examined MHR in familial Mediterranean fever (FMF) patients, it was reported that a positive correlation was detected between inflammation parameters (e.g., CRP, serum amyloid A, fibrinogen, erythrocyte sedimentation rate, and MHR)." (PMID 36836510, 2023).
hemophagocytic lymphohistiocytosis (10 papers, 2017 to 2025). "The pathophysiological mechanisms have not been elucidated, but concordant increases of troponins and inflammatory markers such as interleukin-6, C-reactive protein (CRP), and D-dimer have suggested systemic inflammation and secondary hemophagocytic lymphohistiocytosis as a potential cause." (PMID 39203980, 2024). "However, serum ferritin and CRP increased moderately, with a slight D-dimer increase and incompliance with hemophagocytic syndrome diagnostic criteria." (PMID 35311051, 2022). "Daily monitoring for elevated C-reactive protein and ferritin levels may identify patients at greater risk for severe CRS and hemophagocytic lymphohistiocytosis." (PMID 30564474, 2018). "Hemophagocytic syndrome/Hemophagocytic lymphohistiocytosis (HLH) was also considered in the differential diagnosis given the markedly elevated ferritin, LDH, liver enzyme abnormalities as well as elevated C - reactive protein and d-dimers." (PMID 40590912, 2025).
Hirsutism (10 papers, 2018 to 2025). Abnormally increased hair growth referring to a male pattern of body hair (androgenic hair). "Correlation analysis showed that serum CRP correlated positively with hirsutism (rs = 0.343; p = 0.012) and hair loss (rs = 0.245; p= 0.047)." (PMID 39036884, 2024). "The results of this investigation suggest that a positive correlation exists between CRP levels and clinical manifestations of HA (hirsutism and hair loss)." (PMID 39036884, 2024). "Vit D supplementation resulted in significant reductions in total testosterone, free androgen index, hirsutism, and C-reactive protein (CRP) levels, as well as a significant increase in sex hormone binding globulin and total antioxidant capacity 29,30." (PMID 40777956, 2024). "They obtained beneficial effects overall on mental health parameters, total serum testosterone, hirsutism, high sensitivity for C-reactive protein, total plasma antioxidant capacity, total glutathione, and malondialdehyde levels." (PMID 37570422, 2023). "We found that the co-administration of probiotic and selenium for 12 weeks to women with PCOS had beneficial effects on mental health parameters, serum total testosterone, hirsutism, hs-CRP, TAC, GSH and MDA levels." (PMID 30217229, 2018).
lung adenocarcinoma (10 papers, 1998 to 2023). A carcinoma that arises from the lung and is characterized by the presence of malignant glandular epithelial cells. "We found that two genes in lung adenocarcinoma had enriched mutations in their pocket regions: CRP (P = 4.9 × 10-7) and PLEK (P = 2.1 × 10-3)." (PMID 25360158, 2014). "The combined prognostic role of IL-6, CRP plus IL-17A in stage I lung adenocarcinoma has not been reported previously." (PMID 28402963, 2017). "In the first comparison, proteins which most contributed to discriminate between 58 malignant (of which half were lung adenocarcinomas and half mesotheliomas) and their corresponding paired TB effusions were MMP-9, cathepsin-B, C-reactive protein, angiostatin, and chondroitin sulfate." (PMID 26962828, 2016).
Lyme disease (10 papers, 2010 to 2025). Lyme disease (named after the towns in the USA where the disease was first identified) is a bacterial infection caused by Borrelia burgdorferi. "Lyme disease has shown various CRP concentrations, and a study concluded that that CRP seems highest when the concentration of spirochetes is highest in the skin and/or bloodstream, and it decreases after the organism’s dissemination to extracutaneous sites in subsequent stages of infection." (PMID 37873776, 2023). "There was also evidence of elevated inflammatory markers, including elevated sedimentation rates (ESR), C-reactive protein (CRP), and C3a/C4a, in most of our patients, although the latter can be seen with both Lyme disease and toxic mold exposure." (PMID 30400667, 2018). "Infection with B. burgdorferi clearly stimulates the coordinated production CRP and SAA along with IL-6 during the acute stage of Lyme disease." (PMID 24740099, 2014).
metabolic acidosis (10 papers, 2014 to 2025). "The level of all nutritional factors, except prealbumin, significantly decreased with mGFR decline, while that of inflammation factors (except CRP) as well as the prevalence of metabolic acidosis significantly increased." (PMID 25401694, 2014). "Macrophages exposed to acidic uremic environment stimulate the production of tumor necrosis factor-α (TNF-α), initiating the acute phase response and leading to an increased concentration of C-reactive protein (CRP), which correlates with metabolic acidosis." (PMID 29324682, 2018).
metastatic colorectal cancer (10 papers, 2012 to 2025). "Meta-analysis of the correlation between C-reactive protein to albumin ratio and clinicopathological characteristics of metastatic colorectal cancer." (PMID 34797305, 2021). "In recent years, several observational studies have investigated the association between C-reactive protein to albumin ratio (CAR) and prognosis of metastatic colorectal cancer (mCRC), and yielded controversial outcomes." (PMID 34797305, 2021). "This has been previously explored in a small study by Read and colleagues in patients with metastatic colorectal cancer that suggested that there is a correlation with CRP and PGSGA." (PMID 22433965, 2012). "The CRP/ALB ratio is a useful marker not only for predicting survival, but also for monitoring chemotherapeutic effectiveness in patients with unresectable metastatic colorectal cancer who receive palliative chemotherapy." (PMID 27812440, 2016). "The CRP/ALB ratio is a useful marker for predicting survival and monitoring chemotherapeutic effectiveness in patients with unresectable metastatic colorectal cancer." (PMID 27812440, 2016). "The aim was to explore the prognostic significance of IL-6 and markers of systemic inflammatory response (SIR), in particular C-reactive protein (CRP), in metastatic colorectal cancer (mCRC) patients, in the total study population and according to RAS and BRAF mutation status." (PMID 27738330, 2016).
myxoma (10 papers, 2011 to 2024). A benign soft tissue neoplasm characterized by the presence of spindle and stellate cells, lobulated growth pattern, and myxoid stroma formation. "Clinical features of myxomas encompass a triad of arterial embolism, obstruction of intracardiac blood flow, and constitutional signs often include fatigue, fever, weight loss, and elevated CRP." (PMID 32138674, 2020). "This case involves a patient with intermittent fevers, fatigue, and elevated C-reactive protein (CRP) that was eventually attributed to a myxoma." (PMID 32138674, 2020). "The higher IL-6 and CRP levels inpatients with sessile cardiac myxoma might implicate that more cells or exposedendothelium might remain in the large sessile myxomas." (PMID 30810670, 2019). "Keeling and coworkers found significant immunological alterations in myxoma patients that seemed to occur pre- and postoperatively, including serum protein electrophoresis, C-reactive protein, fluorescence-activated cell sorter, interleukin 2 receptor, and intracellular adhesion molecule (ICAM)." (PMID 23554713, 2011). "Increased NT-proBNP and inflammatory markers such as WCB count, CRP, and ESR are reported in patients with RA myxoma." (PMID 39266935, 2024). "The myxoma was resected; however, 1-week postoperation hemoglobin and blood pressure decreased with elevated erythrocyte sedimentation rate (ESR) and C-reactive protein (CRP)." (PMID 38105244, 2023).
nephrotic syndrome (10 papers, 2020 to 2025). A collection of symptoms that include severe edema, proteinuria, and hypoalbuminemia; it is indicative of renal dysfunction. "As both the CRP/albumin ratio and fluid overload were parameters of interest in the study, the number of exclusion criteria was higher, reducing the generalizability to children with conditions like congenital heart disease or nephrotic syndrome." (PMID 39764324, 2025). "However, some case reports have shown elevated CRP levels in patients with nephrotic syndrome and nocardiosis, with levels reaching around 100 mg/L." (PMID 39597048, 2024). "CRP can be deposited in kidney lesions in glomerular diseases, whereas significant CRP loss via urine is not as reported in children Nephrotic Syndrome (NS); therefore, serum CRP could possibly be a reliable marker of NS inflammation." (PMID 37873776, 2023). "Early neutrophil-to-lymphocyte ratio (NLR) and C-reactive protein (CRP) values are significantly predictive of relapse and poor prognosis within one year for children with steroid-sensitive nephrotic syndrome (SSNS)." (PMID 40078589, 2025). "This study aims to investigate the predictive value of early neutrophil-to-lymphocyte ratio (NLR) and C-reactive protein (CRP) levels for relapse and adverse prognosis within one year in children diagnosed with steroid-sensitive nephrotic syndrome (SSNS)." (PMID 40078589, 2025). "Immune system derangements resulting in an inflammatory state have been described during proteinuria in nephrotic syndrome and include a few mediators of inflammation, like IL17 A, TNF-α, IFN-γ, TLR-3, and CRP." (PMID 33585371, 2020). "C-reactive protein decreased in relation to the increase in serum albumin due to proteinuria reduction, even if the patients did not have full-blown nephrotic syndrome." (PMID 38892620, 2024).
renal colic (10 papers, 2012 to 2025). A severe intermittent and spasmodic pain in the lower back radiating to the groin, scrotum, and labia which is most commonly caused by a kidney stone (RENAL CALCULUS) passing through the URETER or by other urinary track blockage. "In another study, age and a high CRP level were associated as useful parameters for deciding upon emergency drainage in patients with renal colic due to upper urinary tract calculi." (PMID 24037335, 2014). "CRP is also considered to be a valid parameter for assessing whether to undergo urethral stenting in patients with renal colic caused by urinary stones, and is more informative than serum creatinine and leukocyte levels." (PMID 38281018, 2024). "Of 1,096 CT examinations during the study window, 233 were for suspected renal colic; 58 patients met eligibility and had admission CRP available (29 with CRP < 5 mg/L and 29 with CRP ≥ 5 mg/L)." (PMID 41204018, 2025). "The top five important characteristics in the LR, XGBoost, RF and GBDT models include CRP, renal colic and HU value of effusion." (PMID 38896174, 2024). "The top five characteristics in the four models of LR, XGBoost, RF, and GBDT include CRP, renal colic, and HU value of effusion." (PMID 38896174, 2024). "The foremost clinical characteristic in the XGBoost model is CRP, which is followed by hemoglobin, blood glucose, renal colic, globulin and HU value of effusion." (PMID 38896174, 2024). "CRP remains the most crucial clinical characteristic, followed by renal colic, HU value of effusion, G/A, IL-6, globulin, and PCT." (PMID 38896174, 2024). "In our patient, on first attendance, the clinical status was severe left renal colic pain, high CRP and WBC values, and fever episodes." (PMID 35614450, 2022). "Although CRP levels were statistically higher in renal colic patients, the clinical significance of this change (from 0.4 to 0.47mg/L) is questionable." (PMID 34260177, 2021). "We aimed to determine whether serum CRP can predict the presence of complicated calculus or alternative pathology in patients with suspected renal colic." (PMID 41204018, 2025). "CRP plays a crucial role in predicting the failure of spontaneous stone expulsion in lower urinary tract stones and serves as a marker for urinary tract obstruction in renal colic patients." (PMID 38281018, 2024). "In another study, a high CRP level and old age were found to be independent predictors of the need for urinary diversion, and CRP was shown to be an objective and useful parameter for the selection of stenting in patients with renal colic." (PMID 22413829, 2012).
rhabdomyolysis (10 papers, 2012 to 2025). Necrosis or disintegration of skeletal muscle often followed by myoglobinuria. "In accidents involving Africanized bees, strong inflammation and cell damage are observed since AmV causes rhabdomyolysis, hemolysis, and renal and peripheral blood mononuclear cell necrosis and elevates CRP levels." (PMID 39606222, 2024). "However, we did not observe an association of changes of cystatin C levels and CRP, NT-proBNP or CK after the race among our runners that would indicate a substantial inflammatory trigger, acute cardiorenal syndrome or rhabdomyolysis, respectively, as causes for the altered renal function." (PMID 25889047, 2015). "Medians and ranges for selected cytokines, CRP, insulin and cortisol before (day 0) and after successfully completing day 4 of the 2015 Yukon Quest and 5 dogs with exertional rhabdomyolysis (ER)." (PMID 30073172, 2018). "They initially reported that the likely cause of her rhabdomyolysis was viral myositis, however continued to work up different etiologies of rhabdomyolysis by ordering a muscle biopsy, ANA IFA with reflex, ESR/CRP, myositis panel, C3/C4, SSA/SSB, RF, and aldolase." (PMID 37170192, 2023). "During the episode of rhabdomyolysis in 2016, her creatine kinase (CK) level was 205 IU/L (Reference Range; RR 25–200 IU/L), erythrocyte sedimentation rate (ESR) was 51 mm/h (RR 5.0–15 mm/h) and C-reactive protein (CRP) was 10 mg/L (RR 0–5 mg/L)." (PMID 36298810, 2022).
Still’s disease (10 papers, 2014 to 2026). "Patients included in GIRRCS AOSD-study group and AIDA Network Still Disease Registry were assessed if variables for cluster analysis were available (age, systemic score, erythrocyte sedimentation rate (ESR), C reactive protein (CRP) and ferritin)." (PMID 37989322, 2023). "The guideline also provides a simple definition for CID: absence of Still’s disease-related symptoms and normal ESR/CRP, with remission being a period of at least 6 months with CID." (PMID 41281302, 2025).
typhoid fever (10 papers, 2015 to 2024). A bacterial infectious disorder contracted by consumption of food or drink contaminated with Salmonella typhi. "Further analysis performed on the clinical data around typhoid diagnosis showed that ViTT recipients had lower median C-reactive protein (CRP) levels after diagnosis of typhoid fever." (PMID 37402153, 2023). "Compared to 114 patients with NTS infections, 16 patients with typhoid fever presented with higher levels of CRP and PCT (P < 0.05)." (PMID 36040531, 2022). "Despite a negative Salmonella Typhi IgM rapid test result, the patient was diagnosed as having typhoid fever based on clinical presentation and elevated inflammatory biomarkers C-reactive protein (CRP) and procalcitonin." (PMID 30445913, 2018).
AA amyloidosis (9 papers, 2013 to 2025). Secondary amyloidosis is a form of amyloidosis, that complicates chronic inflammatory disorders (mainly rheumatoid arthritis) and is characterized by the aggregation and deposition of amyloid fibrils composed of serum amyloid A protein, an acute phase reactant. "In the two previously reported cases of IgG4-RD associated with secondary AA amyloidosis, elevated levels of CRP were also observed." (PMID 41280944, 2025). "Because serum amyloid A (SAA) is directly involved in the pathogenesis of reactive amyloidosis (i.e., AA amyloidosis), it has been suggested that it may be a better marker for disease control and risk of AA amyloidosis than CRP in humans." (PMID 39814065, 2025). "Symptomatic CAPS is accompanied by a striking acute-phase response, with serum concentrations of C-reactive protein (CRP) and serum amyloid A protein (SAA) frequently elevated by 100- to 1,000-fold, underlying the high risk of AA amyloidosis." (PMID 23421920, 2013). "The subclinical inflammation may continue during attack-free periods in FMF patients, and despite reflecting attacks with high sensitivity, value of the classical acute phase reactants (ESR and CRP) for the prediction of subclinical inflammation may progress to AA amyloidosis." (PMID 34912764, 2021). "Serum C-reactive protein and SAA correlate highly, and given the association between malignancies and serum amyloid A concentrations, a plausible hypothesis for the origin of our patient's AA amyloidosis would be a high SAA titre produced by the NSCLC." (PMID 24558629, 2013). "Therefore, we speculated that in our case, the elevated CRP level not only indicated the severity of the inflammatory response in these patients but also suggested the presence of high levels of SAA in blood, which finally led to the occurrence of AA amyloidosis." (PMID 41280944, 2025). "A decrease in the median CRP and proteinuria values was observed with bDMARDs, but creatinine values continued to increase along the course of the disease, and similar results were observed in both FMF-AA amyloidosis and non-FMF-AA amyloidosis (available at Rheumatology online)." (PMID 37738242, 2024).
acute lung injury (9 papers, 2016 to 2025). A condition of lung damage that is characterized by bilateral pulmonary infiltrates (pulmonary edema) rich in neutrophils, and in the absence of clinical heart failure. "Although CRP potently predicts adverse outcome in these diseases, experimental data suggest that CRP may instead play a protective role in alveolitis and previous clinical evidence reported that elevated levels of CRP were associated with decreased mortality among patients with acute lung injury." (PMID 34506514, 2021). "There is a correlation between increased levels of C-reactive protein and D-dimer and increased hypoxemia, which supports the role of thromboinflammation in acute lung injury observed in patients with Covid-19." (PMID 32984388, 2020). "In patients with acute lung injury, sivelestat sodium more effectively reduced IL-6, TNF-α, and CRP levels (in comparison with doxofylline), and significantly increased the oxygenation index at 24 and 72 h." (PMID 40842872, 2025).